APOC3 (apolipoprotein C3)
Diseases named in the same sentence as APOC3 in open-access papers (continued):
Sharing a sentence is not in itself a finding about the gene and the disease.
lipid metabolism disorders (6 papers, 2014 to 2025). "The small-molecule peptides in the earthworm protein hydrolysate alleviated lipid metabolism disorders in steatotic hepatocytes by regulating the expression levels of crucial proteins (APOC3, HMGCR, PCSK9, PPAR-Y, SREBP1, C/EBP-a, NPC1L1, CYP7A1)." (PMID 40647090, 2025). "Relevant studies have shown that APOC3 is not only involved in the occurrence and development of various diseases, such as cardiovascular diseases and glucose and lipid metabolism disorders, but also participates in other physiological and pathophysiological processes." (PMID 39928771, 2025).
Sepsis (6 papers, 2017 to 2023). Sepsis is defined as life-threatening organ dysfunction caused by a dysregulated host response to infection. "New diagnostic biomarkers of sepsis were screened by iTRAQ2D‐LC MS/MS, and proteins of ApoC3, VCAM1, B2M, and ApoE provide a supplement to classical biomarkers for septic diagnosis." (PMID 34825737, 2022). "The level of ApoC3 was gradually decreased among non‐sepsis, sepsis, and septic shock groups (p = 0.049)." (PMID 34825737, 2022). "In our study, serum ApoC3 level was gradually decreased among non‐sepsis, sepsis, and septic shock groups, which was mainly secreted by the liver, as a potential biomarker for the liver pathogenesis." (PMID 34825737, 2022). "In a previous plasma proteomic analysis of 10 sepsis patients, expression of APOC3 was statistically significantly downregulated the day after the suspected septic episode began compared with immediately after an elective surgical procedure." (PMID 35336960, 2022). "An index combining the levels of four proteins (β2-microglobulin >3.7 mg/L, VCAM1 >2216.8 ng/mL, ApoC3 ≤54.532 μg/mL, ApoE >62.45 mg/L) and two conventional infection biomarkers (procalcitonin, C-reactive protein yielded an AUC of 0.772 for sepsis identification." (PMID 36831207, 2023). "The investigators hypothesized that VCAM1 reflected endothelium dysfunction, β2-microglobulin reflected sepsis-induced kidney, ApOC3 reflected hepatic secretory function, and ApoE reflected coagulation system failure." (PMID 36831207, 2023). "ApoC3 glycol‐isoform ratios were altered in patients with sepsis and other severe systemic diseases, which might be an important indicator for diagnostic, prognostic, and therapeutic status." (PMID 34825737, 2022). "In this study, the combination of ApoC3, VCAM1, B2M, and ApoE proteins were screened and identified as biomarkers for sepsis by using iTRAQ‐2D‐LC‐MS/MS method." (PMID 34825737, 2022). "A study evaluating changes in serum proteome between sepsis and non-sepsis groups found that a downregulation of ApoC3 presented good discrimination properties between the two study groups." (PMID 36459524, 2022). "Patients with sepsis had lower ApoC3 expression than non-septic patients." (PMID 36459524, 2022).
steatosis (6 papers, 2011 to 2025). Increased lipid within the cytoplasm of cells. "By the mild increase in their steatosis scoring, an association was highlighted between APOC3 rs2070667 and hepatocyte steatosis." (PMID 33294458, 2020). "In total, we identified 27 genes, of which 3 are monogenic causes of steatosis (APOB, G6PC1, PPARG), 4 were previously associated with MASLD (APOB, APOC3, INSR, PPARG), and 23 had supporting clinical, experimental, and/or genetic evidence." (PMID 40065360, 2025). "The treatment with curcumin-andrographolide in association maintained the ability to regulate in a negative manner FABP1 (15.96 times), PPARGC1A (7.85 times), GK and ABCA1 (4 times), and APOC3 (2.04 times) in respect to the steatosis control." (PMID 36770927, 2023). "Scoring of hepatocyte steatosis, ballooning, lobular inflammation, and liver fibrosis was then performed to reveal the role of lipidomics-affecting APOC3 SNPs in NAFLD-specific pathological alterations." (PMID 33294458, 2020). "By scoring hepatocyte steatosis, lobular inflammation, ballooning, and liver fibrosis, we assessed the role of APOC3 rs2070667 in NAFLD-related pathological characteristics." (PMID 33294458, 2020). "In detail, we found the down expression of FABP1 (40 times) and APOC3 (11.98 times), PPARGC1A and GK (11 times), ABCA1 and SRBF2 (3 times) compared to the steatosis control." (PMID 36770927, 2023). "In our experiments, the downregulation of genes involved in lipid/cholesterol metabolism and transport (such as FABP1, APOC3, PPARGC1A, GK, ABCA1, and SRBF2) induced by curcumin treatment could explain the observed reduction of steatosis and lipid content." (PMID 36770927, 2023).
coronary artery calcification (5 papers, 2016 to 2024). Calcification of the coronary artery, used as a measure of coronary atherosclerosis, a risk factor for myocardial infarction. "Genetic studies have also shown that carriers of the APOC3 null mutation R19X have 50% lower plasma apoC-III levels, 35% lower plasma triglycerides, markedly lower postprandial triglycerides and significantly lower coronary artery calcification (CAC) scores than non-carriers." (PMID 32849270, 2020).
depression (5 papers, 2016 to 2024). "Combining KXS drastically ameliorated the Hamilton Depression 17 (HAM-D17) rating scores and self-rating depression scale scores, and the serum lipoprotein B, apolipoprotein C3 and albumin levels and low-density lipoprotein cholesterol/high-density lipoprotein cholesterol ratio." (PMID 38362144, 2024).
glaucoma (5 papers, 2018 to 2021). Increased pressure in the eyeball due to obstruction of the outflow of aqueous humor. "This agrees with previous investigations wherein elevated levels of both APOA1 and APOC3 were detected among individuals with glaucoma." (PMID 34602085, 2021). "LDL and HDL are two key nodes in the network, and APOC3, NPC2, LDL, and HDL are connected to cholesterol, strengthening the evidence that lipid metabolism pathway proteins are upregulated in AH from glaucoma patients." (PMID 29847670, 2018). "Among the identified proteins significantly altered in glaucoma, eight were further studied using semi-targeted or targeted approaches, showing higher levels of ALB, APOC3, CysC, TIMP2, A2M, PGTDS, and ENPP2, and lower levels of SOD1, in POAG patients compared to control subjects." (PMID 34439995, 2021).
lung carcinoma (5 papers, 2019 to 2024). "Our findings strongly advocate for heightened vigilance concerning the potential for APOC3 inhibitors to increase lung cancer risk." (PMID 38034491, 2023). "Neutral ceramidase mediated 8.1% and 9.5% of the reduced lung cancer risk in ever-smokers via ApoB and TG reduction by APOB inhibition, respectively, and mediated 8.7% of the reduced LUAD risk via ApoB reduction by APOC3 inhibition." (PMID 38034491, 2023). "In this drug-target MR analysis, we assessed the effects of LLDs on lung cancer risk via six LLD targets (APOB, APOC3, HMGCR, LPL, NPC1L1, and PCSK9), comprising 12 lipid-lowering pathways." (PMID 38034491, 2023). "The observed mediation effects highlight the considerable influence of neutral ceramidase on lung cancer risk reduction achieved by APOB and APOC3 inhibition." (PMID 38034491, 2023). "In contrast to previous MR analysis of the effects of statins on lung cancer risk, our study reveals novel findings that HMGCR inhibition increases the risk of SCLC, as does APOC3 inhibition." (PMID 38034491, 2023). "Associations of APOB, APOC3, and HMGCR inhibition and the LPL agonist with distinct lung cancer risks underscore the multifaceted nature of these relationships." (PMID 38034491, 2023). "Immunohistochemical assessments of lung cancer tissue samples have unveiled lower protein expression of APOC3 in SCLC compared to normal lung tissue." (PMID 38034491, 2023). "Associations of APOB, APOC3, and HMGCR inhibition and LPL agonist with distinct lung cancer risks underscore the multifaceted nature of these relationships." (PMID 38034491, 2023). "The observed mediation effects highlight the considerable influence of neutral ceramidase on the lung cancer risk reduction achieved by APOB and APOC3 inhibition." (PMID 38034491, 2023). "Furthermore, an investigation under the UK’s Early Access to Medicines Scheme reported instances of lung cancer metastasis after the prolonged utilization of APOC3 inhibitors (volanesorsen)." (PMID 38034491, 2023).
uremia (5 papers, 2014 to 2022). A clinical syndrome associated with the retention of renal waste products or uremic toxins in the blood. "Compared to controls, uremia patients had significantly increased L5% (P < 0.001) and L5 that was rich in apolipoprotein C3 and triglycerides." (PMID 26765403, 2016).
amyloidosis (4 papers, 2016 to 2025). A disorder characterized by the localized or diffuse accumulation of amyloid protein in various anatomic sites. "In addition to neurogenesis, cell adhesion/inflammation, and synaptic signaling, cholesterol metabolism, and especially lipoproteins (APOA1, APOC1, APOC3, APOF), were associated with depressive symptoms when amyloid pathology was present." (PMID 41451799, 2025). "Based on the fact that affected patients with amyloidosis also displayed hypotriglyceridemia and increased plasma levels of HDL-C as compared with non-carriers in the family, we next screened several candidate genes including the APOC3, APOC1, APOC2, APOC4, APOA4, APOA5 and APOE genes." (PMID 26790392, 2016).
gout (4 papers, 2014 to 2021). A condition characterized by painful swelling of the joints, which is caused by deposition of urate crystals. "The APOC3 (rs5128) gene has a causal role in gout, decreasing the risk of gout and increasing expression of APOC3." (PMID 33926105, 2021). "Previously, we reported an association of triglycerides, and in particular VLDL triglycerides, with gout, as well as an association of a triglyceride-decreasing apolipoprotein C3 (APOC3) variant (rs5128) with decreased risk of gout." (PMID 28679452, 2017).
liver disease (4 papers, 2017 to 2025). "Collectively, our findings demonstrated therapeutically relevant expression using a precise and efficient APOC3-editing platform, providing insights into the development of further long-term therapeutics for diverse monogenic liver diseases." (PMID 36090746, 2022).
ovarian carcinoma (4 papers, 2009 to 2024). A malignant neoplasm originating from the surface ovarian epithelium. "Although APOC2 has been implied as a biomarker in pancreatic and cervical cancer, an overexpression of APOC3 has been described in ovarian cancer and in the recurrent disease of small-cell lung cancer patients." (PMID 39194522, 2024).
rheumatoid arthritis (4 papers, 2015 to 2022). A chronic, systemic autoimmune disorder characterized by inflammation in the synovial membranes and articular surfaces. "In our study, in patients with rheumatoid arthritis, circulating ApoC3 was also significantly correlated with serum triglyceride levels." (PMID 35637531, 2022).
schizophrenia (4 papers, 2019 to 2024). A major psychotic disorder characterized by abnormalities in the perception or expression of reality. "A meta-analysis between schizophrenia patients and healthy controls was performed, with the results suggesting four apolipoproteins, APOA1, APOA2, APOC1 and APOC3 (downregulated), and ficolin-3 (upregulated) as potential biomarkers of the disorder." (PMID 35563307, 2022).
colorectal cancer (3 papers, 2021 to 2023). A primary or metastatic malignant neoplasm that affects the colon or rectum. "Previous studies found that APOC3, F2, and AHSG were critical factors within LM of colorectal cancer and may be used as novel biomarkers for predicting the LM of colorectal cancer." (PMID 37770976, 2023).
psoriasis (3 papers, 2020 to 2025). An autoimmune condition characterized by red, well-delineated plaques with silvery scales that are usually on the extensor surfaces and scalp. "The aim of this study was to evaluate the potential associations between serum concentrations of apolipoproteins (ApoA1, ApoA2, ApoB, ApoC1, ApoC3, ApoD, ApoE, ApoH, and ApoJ) and various clinical and biochemical markers in patients with psoriasis." (PMID 40137160, 2025). "While limited prior research has primarily focused on apolipoproteins such as ApoA1, ApoA2, ApoB, ApoC1, ApoC3, and ApoE in psoriasis, our study uniquely extends this scope by also evaluating ApoD, ApoH, and ApoJ in this patient population for the first time." (PMID 40137160, 2025). "While ApoA1 and ApoB in psoriasis have been the primary focus of research due to their established roles in lipid metabolism and cardiovascular risk, other apolipoproteins, such as ApoA2, ApoC1, ApoC3, ApoD, ApoE, ApoH, and ApoJ, have not been widely studied in psoriasis." (PMID 40137160, 2025).
venous thromboembolism (3 papers, 2019 to 2023). Occlusion of the lumen of a vein by a thrombus that has migrated from a distal site via the blood stream. "Results for apolipoprotein C3 (APOC3) and lipoprotein lipase (LPL) followed a pattern more similar to the analysis for triglycerides, showing inverse associations with thromboembolic diseases (P=0.007 for APOC3, P=0.089 for LPL for any venous thromboembolism)." (PMID 31756303, 2019).
acute coronary syndrome (2 papers, 2014 to 2015). Signs and symptoms related to acute ischemia of the myocardium secondary to coronary artery disease. "A case–control study found that the minor alleles of APOC3 −455 T/C polymorphisms were closely associated with acute coronary syndrome." (PMID 25994187, 2015). "A case–control study suggested that the minor alleles of APOC3 -455 T/C polymorphisms were closely associated with acute coronary syndrome." (PMID 25380998, 2014).
asthma (2 papers, 2021 to 2024). "Consistent with previous studies, we found that an increased TG level driven by the APOC3(OR = 1.0086, 95%CI: 1.0037–1.0135) and LPL (OR = 1.0040, 95%CI: 1.0001–1.0078) target were associated with an increased risk of asthma." (PMID 38961500, 2024). "In this study, we found that TG levels driven by the APOC3, and LPL targets were associated with an increased risk of asthma." (PMID 38961500, 2024). "The elevated triglyceride (TG) levels associated with the APOC3, and LPL targets were found to increase asthma risk." (PMID 38961500, 2024).
cataract (2 papers, 2021). Partial or complete opacity of the crystalline lens of one or both eyes that decreases visual acuity and eventually results in blindness. "Conversely, female POAG patients had significantly greater levels of APOA1 (FC = 1.36; p < 0.01), APOA2 (FC = 1.21; p = 0.03), APOA4 (FC = 1.30; p = 0.04), APOC3 (FC = 1.38; p = 0.01), and APOD (FC = 1.20; p = 0.04) compared to cataract patients." (PMID 34602085, 2021). "APOA1, APOC3, and APOE have been shown to be elevated in the AH of POAG patients as compared to patients with cataracts." (PMID 34602085, 2021).
Cognitive impairment (2 papers, 2009 to 2020). Abnormal cognition is characterized by deficits in thinking, reasoning, or remembering. "Despite limited evidence for associations between APOC3 genotype and cognition, linkages between APOC3 SNPs and the metabolic dysregulation which may accompany cognitive impairment in older individuals provide potential mechanistic explanations for the associations we observed." (PMID 19424489, 2009).
E. coli infection (2 papers, 2018 to 2019). "A number of genes involved in fatty acid transport, such as fatty acid-binding protein 1 (Fabp1) and four apolipoproteins (Apoa1, 2, 5 and Apoc3), were downregulated by E. coli infection in Mkp-1+/+ mice." (PMID 30563203, 2018).
gestational hypertension (2 papers, 2014). "Mice in ApoC3+NS only exhibited mild gestational hypertension, but after L-NA injection, the mean arterial pressure (MAP) and urinary protein levels were higher for ApoC3+L-NA than ApoC3+NS mice (P<0.05), with PE-like symptoms." (PMID 25302499, 2014).
heart failure (2 papers, 2014 to 2023). Inability of the heart to pump blood at an adequate rate to meet tissue metabolic requirements. "About 2% of the study participants had at least one side effect (hyperlactaemia, heart failure, or dry skin) linked to the use of stavudine, although 35% of the patients harboured the APOC3 −455CC allele." (PMID 24972136, 2014). "Findings from GWAS and Mendelian randomization-proteomics identify seven (CAMK2D, PRKD1, PRKD3, MAPK3, TNFSF12, APOC3 and NAE1) proteins as potential targets for interventions to be used in primary prevention of heart failure." (PMID 37429843, 2023).
lung adenocarcinoma (2 papers, 2021 to 2023). A carcinoma that arises from the lung and is characterized by the presence of malignant glandular epithelial cells. "APOC3 inhibition decreased the lung adenocarcinoma (LUAD) risk (OR 0.60, 95% CI 0.43–0.84, p = 0.039) but increased SCLC risk (OR 2.18, 95% CI 1.17–4.09, p = 0.029) via ApoB reduction by 1 SD." (PMID 38034491, 2023). "For example, Xu and Chen utilized a six AG-based pattern (APOC3, EPOR, H2AFX, MXD1, PLCG2, and YWHAZ) to structure a risk model that could efficiently stratify the existing cases in high- and low-risk groups in terms of OS in lung adenocarcinoma (LUAD)." (PMID 34976839, 2021).
lupus nephritis (2 papers, 2022). Glomerulonephritis in the context of systemic lupus erythematosus. "The authors of this study, which intended to analyze how different oxidate serum proteins vary between SLE and controls, suggested that ApoC3 could be a biomarker in the subset of patients with lupus nephritis." (PMID 35538496, 2022). "In a previous work, in a study that included 17 healthy subjects and 33 patients, ApoC3 levels were significantly elevated in lupus nephritis patients compared to controls or non-renal SLE patients." (PMID 35615358, 2022). "In a report on 9 controls, 21 SLE patients, and 11 lupus nephritis patients, total ApoC3 levels were significantly increased in lupus nephritis patients compared to controls or non-renal SLE patients." (PMID 35538496, 2022).
artery disease (1 paper, 2024). "Inline with our expectations, our genetically proxied instruments forPCSK9, HMGCR, CETP and APOC3 in the Mendelianrandomization analysis demonstrated a noteworthy reduction in susceptibility tocoronary artery disease." (PMID 39228495, 2024).
bacterial pneumonia (1 paper, 2022). Acute infection of the lung parenchyma caused by bacteria (e.g., Streptococcus pneumoniae, Haemophilus influenzae, Chlamydia pneumoniae, Mycoplasma pneumoniae, and Legionella pneumophila). "APOC3 and GPLD1 are involved in lipid metabolism, which has been shown to be dysregulated in bacterial pneumonia, thereby associated with unfavorable outcomes." (PMID 36812516, 2022).
cerebrovascular disease (1 paper, 2009). "Variant alleles of both APOC3 3u386 and APOC3 m482 were associated with unfavorable lipid and glucose markers which contribute to cardiovascular and cerebrovascular disease risk." (PMID 19424489, 2009).
chronic hepatitis B (1 paper, 2019). "Serum apolipoprotein C3 (ApoC3) and apolipoprotein A5 (ApoA5) levels were decreased in chronic hepatitis B (CHB) patients, however the relationship between ApoC3 or ApoA5 and HBV DNA load remains elusive." (PMID 31186008, 2019).
colitis (1 paper, 2024). Inflammation of the colon. "Overall, the findings indicate that the impact of HFD on DSS‐induced colitis may be linked to intestinal dysbiosis and specific genes such as Abca8b, Ace2, Apoa1, Apoa4, Apoc3, Aspa, Dpp4, Maob, Slc34a2, Slc7a9, and Trpm6." (PMID 39479684, 2024). "Impact of HFD on DSS‐induced colitis may be linked to intestinal dysbiosis and specific genes such as Abca8b, Ace2, Apoa1, Apoa4, Apoc3, Aspa, Dpp4, Maob, Slc34a2, Slc7a9, and Trpm6." (PMID 39479684, 2024).